CTU1 (cytosolic thiouridylase subunit 1)
Description:
Plays a central role in 2-thiolation of mcm(5)S(2)U at tRNA wobble positions of tRNA(Lys), tRNA(Glu) and tRNA(Gln). Directly binds tRNAs and probably acts by catalyzing adenylation of tRNAs, an intermediate required for 2-thiolation. It is unclear whether it acts as a sulfurtransferase that transfers sulfur from thiocarboxylated URM1 onto the uridine of tRNAs at wobble position.
Synonyms: ATPBD3; NCS6; MGC17332
Tractability: PROTAC: ubiquitination databases record sites on it.
Gene: Protein-coding gene on chromosome 19 (51,097,606 to 51,108,424, reverse strand). Ensembl gene ENSG00000142544.
Subcellular location: Cytoplasm
Subcellular location (Human Protein Atlas): Cytosol
Pathways (Reactome):
Metabolism of RNA: tRNA modification in the nucleus and cytosol
Gene Ontology:
Molecular function: protein binding; tRNA binding; nucleotidyltransferase activity
Biological process: tRNA thio-modification; tRNA wobble position uridine thiolation; tRNA wobble uridine modification; protein urmylation; tRNA processing
Cellular component: cytosol; cytosolic tRNA wobble base thiouridylase complex; cytoplasm
Genetic constraint (gnomAD): Loss-of-function variants: 17 observed, 7.7 expected, observed/expected ratio (o/e) 2.21. That is too few expected variants to judge how well the gene tolerates losing a copy. Missense variants: 519 observed, 313.78 expected, observed/expected ratio (o/e) 1.65, 90% interval 1.54 to 1.78. Synonymous variants: 279 observed, 154.06 expected, observed/expected ratio (o/e) 1.81, 90% interval 1.64 to 1.96.
Homologues: Orthologues: chimpanzee CTU1 (99% identical), macaque CTU1 (98% identical), dog CTU1 (89% identical), mouse Ctu1 (87% identical), rat Ctu1 (87% identical), guinea pig CTU1 (85% identical), tropical clawed frog ctu1 (51% identical), zebrafish ctu1 (50% identical), Drosophila melanogaster Ctu1 (47% identical), Caenorhabditis elegans tut-1 (43% identical).
Diseases named in the same sentence as CTU1 in open-access papers:
CTU1 is named in the same sentence as 16 diseases in open-access papers, as found by Europe PMC text mining. Sharing a sentence is not in itself a finding about the gene and the disease. The quoted sentences say what the papers report.
breast carcinoma (9 papers, 2018 to 2022). "CTU1 promotes cancer resistance to targeted therapy, its expression is associated with higher rates of morbidity and mortality in spinal cord gliomas, and up-regulation of CTU1 is involved in human breast cancer metastasis." (PMID 34879089, 2021). "It has been reported that CTU1/2, which is partner enzymes in U34 mcm5s2-tRNA modification, sustains metastasis and invasion of breast cancer." (PMID 34863153, 2021). "ELPS and CTU1/2, the enzymes responsible for mcm5s2 modification, were upregulated in breast cancer and promoted metastasis." (PMID 32393790, 2020). "Overexpression of CTU1/2 promotes translation of pro-metastatic genes in breast cancer." (PMID 33564819, 2021). "ELP3 and CTU1/2 were upregulated in human breast cancers and sustained metastasis." (PMID 32393790, 2020). "Moreover, the conserved tRNA thiolase acting on U34 composed of cytosolic thiouridylase subunit 1 and 2 (CTU1/2) have been shown to be up-regulated in human breast cancers and to sustain metastasis." (PMID 32630140, 2020). "Partner enzymes in U34 tRNA modification, including ELP3 and CTU1/2 were found to be up-regulated in human breast cancers and sustain metastasis, through the translation of the oncoprotein DEK, that promotes the translation of the pro-invasive transcription factor LEF1." (PMID 31238876, 2019). "ELP3, CTU1 and CTU2 are also overexpressed in breast cancer, where they maintain high translation levels of the RNA-binding protein DEK1." (PMID 33564819, 2021). "However, its role in CC has not been analyzed yet, but in breast cancer, CTU1 overexpression promotes cell invasion." (PMID 35359376, 2022).
melanoma (5 papers, 2019 to 2022). A malignant, usually aggressive tumor composed of atypical, neoplastic melanocytes. "Additionally, wobble U34 modifications catalyzed by ELP3/CTU1/2 have been shown to drive melanomas that express mutated BRAF, with subsequent resistance to anti-BRAF therapy caused by U34-dependent codon-biased translation of metabolic proteins." (PMID 35327975, 2022). "Depletion of the U34 enzymes Elp3 or cytoplasmic tRNA 2-thiolation protein 1/2 (CTU1/2) provokes cell death in patient-derived BRAFV600E melanoma cultures." (PMID 30921315, 2019).
prostate carcinoma (2 papers, 2021 to 2025). A carcinoma that arises from epithelial cells of the prostate gland. "Two signatures of RNA-binding proteins enrolled the CTU1 gene as a vital indicator to predict the survival of prostate cancer and bladder urothelial carcinoma." (PMID 34745201, 2021).
cervical cancer (1 paper, 2021). A primary or metastatic malignant neoplasm involving the cervix. "What is more, the expression level of CTU1 increased with the N stage, which showed that it might promote the lymph node metastasis of cervical cancer." (PMID 34863153, 2021). "It is displayed in kaplan–Meier curves that higher expression level of EEF1D, CTU1, EIF3C, WDR43, NUFIP1, ZC3HAV1L and PRPF40B indicated a lower overall survival of cervical cancer patients." (PMID 34863153, 2021). "The expression level of CTU1, RBM38, WDR43 varies with different pathology of cervical cancer." (PMID 34863153, 2021). "Furthermore, the expression level of CTU1 and ZC3HAV1L were higher in the advanced T stage patients (P-values = 0.009 and < 0.001 respectively), implying their dangerous roles with the development of cervical cancer." (PMID 34863153, 2021).
ependymoma (1 paper, 2019). A WHO grade II, slow growing tumor of children and young adults, usually located intraventricularly. "In addition, two myxopapillary ependymomas demonstrate amplification of CTU1, a gene critically involved in modification at the wobble position of U34 of certain tRNAs." (PMID 31822682, 2019). "We further identified copy number amplifications in CTU1 in 25% of myxopapillary ependymomas." (PMID 31822682, 2019).
lymph node metastasis (1 paper, 2021). "The expression level of CTU1 was significantly associated with N stages which implying that its expression levels increased with progression of lymph node metastasis." (PMID 34863153, 2021).
pancreatic tumors (1 paper, 2025). "After establishment of pancreatic tumors derived from Ctu1-deficient or control EPP2 cells, animals were treated with rapamycin or vehicle for 9 days." (PMID 40328729, 2025).
venous thromboembolic disease (1 paper, 2022). "For example, the Pitta Kapha replicated profile GWAS SNPs in RASA2, ADK and CTU1 have an association with immuno-metabolic traits and diseases, blood and coagulation related traits/diseases such as venous thromboembolic disease." (PMID 35330488, 2022).
viral infection (1 paper, 2025). "To validate these findings and identify specific components of the modification pathway that are essential for viral infection, we performed shRNA targeted knockdowns of ALKBH8 and CTU1." (PMID 40806605, 2025). "Downstream U34 modification enzymes, ALKBH8 and CTU1, are essential for both SARS-CoV-2 and ZIKV replication—According to the U34 modification pathway, alteration of the two enzymatic steps downstream of the Elongator complex (ELP1-6) step to generate mcm5s2U would also affect viral infection." (PMID 40806605, 2025).
ZIKV infection (1 paper, 2025). "Specifically, ALKBH8 and CTU1 knockdowns both resulted in an approximately 60% reduction in SARS-CoV-2 infection and a 90–95% reduction in ZIKV infection." (PMID 40806605, 2025). "ShRNAs targeting ALKBH8 and CTU1 both led to a significant reduction in SARS-CoV-2 and ZIKV infection levels compared to cells treated with the control shRNA (IRV1)." (PMID 40806605, 2025). "We used an shRNA-based approach to examine the role of ALKBH8 and CTU1, key enzymes acting downstream of Elongator in the U34 pathway, in SARS-CoV-2 and ZIKV infection." (PMID 40806605, 2025).
cancer (5 papers, 2014 to 2025). A tumor composed of atypical neoplastic, often pleomorphic cells that invade other tissues. "By contrast, increased CTU1 activity parallels increased cell growth, as observed in certain types of human cancer." (PMID 24774365, 2014). "CTU1 is involved in cell growth control in certain types of human cancer." (PMID 38630355, 2024).
tumor (4 papers, 2020 to 2025). "In contrast, unmethylation of the CTU1 promoter region gene was associate with stages II and with tumor size <5 cm." (PMID 35359376, 2022). "Whereas, CTU1 was regarded as a tumor accelerating gene because it was up-regulated in high-risk group." (PMID 34863153, 2021). "By contrast, tumor growth was potently suppressed by the combination of Ctu1 deletion and rapamycin treatment." (PMID 40328729, 2025). "REXO2, MSI1, and ESRP2 had high expression levels in tumors compared with normal tissues, while CTU1, MAEL, and YBX2 were undetermined in both tumor and normal tissues." (PMID 33193734, 2020).
CTU1 also shares sentences with these, for which no sentence is quoted: bladder urothelial carcinoma (1 paper); infection (1); retinal disease (1); spinal cord glioma (1).